RYR2 (ryanodine receptor 2)
Diseases named in the same sentence as RYR2 in open-access papers (continued):
Sharing a sentence is not in itself a finding about the gene and the disease.
Arrhythmia (continued). "The existence of both GOF and LOF RyR2 mutations has profound implication for the understanding of RyR2-associated cardiac arrhythmias." (PMID 33825858, 2021). "Loss-of-function (LOF) RyR2 mutations have also been identified and are linked to a distinct entity of cardiac arrhythmia termed RyR2 Ca2+ release deficiency syndrome (CRDS)." (PMID 33825858, 2021). "Which in turn others have appointed this increase in mitochondrial ROS to dysfunctional mitochondria which oxidize the RyR2, developing an increased risk of arrhythmia." (PMID 33585462, 2020). "In fact, pharmacologically induced seizures and brainstem spreading depolarization led to fatal cardiac arrhythmias in mice carrying the gain-of-function mutation RyR2-R176Q." (PMID 32742694, 2020). "The major genes responsible for such inherited arrhythmias are RYR2 (encoding for RYR2), CASQ2 (encoding for calsequestrin-2), and CACNA1C (encoding for CaV1.2)." (PMID 31426283, 2019). "Genetic or PTM of RyR2 are a main cause of Ca2+ triggered arrhythmias, i.e., arrhythmias that are originated due to abnormal Ca2+ handling." (PMID 32038301, 2019). "The role of CaM on RyR2 regulation was highlighted by results that indicate that mutations in CaM are associated with RyR2-mediated cardiac arrhythmias." (PMID 32038301, 2019). "In CPVT patients with mutated RYR2, increased Ca2+ concentration inside the SR can result in spontaneous Ca2+ leakage and in arrhythmias." (PMID 29760739, 2018). "Imbalances in RYR2 expression as well as genetic variants are associated with altered calcium handling and arrhythmia." (PMID 29868113, 2018). "It has been shown that I/R-mediated arrhythmias were associated with CaMKII-dependent phosphorylation of RyR2." (PMID 30574097, 2018). "Mutations in the cardiac ryanodine receptor (RyR2), the ion channel responsible for release of calcium ions from intracellular stores into cytoplasm, are the cause of several inherited cardiac arrhythmias." (PMID 28713282, 2017). "Our findings demonstrate that intravenous dantrolene, a drug used to treat another ryanodine receptor disorder, malignant hyperthermia, abolished or markedly reduced arrhythmias in a subgroup of CPVT1 patients with specific RyR2 mutations." (PMID 25955245, 2015). "Dantrolene seemed to reduce arrhythmias in patients with the mutation in the N-terminal or central region of the RyR2 protein." (PMID 25955245, 2015). "This technique is also applicable in a reciprocal fashion, that is, arrhythmia-causing mutations in RYR2 and SCN5A can be used to interpret novel variants found in any of the paralogues analysed in this study." (PMID 24136861, 2014). "A large number of RyR2 mutations have been associated with cardiac arrhythmias and cardiomyopathies." (PMID 24743769, 2014). "By contrast, our results show that a slowing of RyR2 inactivation would promote calcium alternans and lower the beating frequency where calcium alternans is induced suggesting that these arrhythmias are likely associated with a slowing of RyR2 inactivation." (PMID 23390511, 2013). "Elimination of spontaneously released Ca2+ via RyR2 in diastole can cause a transient sarcolemmal inward current and hence delayed after depolarisations as substrate for cardiac arrhythmias." (PMID 22932727, 2013). "The dysfunction of RyR2 resulting in Ca2+ diastolic leak causing DADs is a feature of fatal arrhythmia in HF and CPVT." (PMID 19345240, 2009). "Furthermore, it was reported that the deletion of PDE4D leads to an increase in RyR2 phosphorylation and an elevated risk of arrhythmias, thereby further accelerating the progression of heart failure." (PMID 40136709, 2025). "Similarly, the alternative splicing of calcium‐regulating genes such as CamkIIδ and Ryr2 has been shown to disrupt calcium homeostasis, significantly increasing the risk of arrhythmias and sudden cardiac death." (PMID 41409803, 2025).
Arrhythmia (continued). "We reasoned that these disease-causing mutant forms of RyR2 would provide insights regarding the structural basis of the diastolic SR Ca2+ leak that promotes HF and fatal cardiac arrhythmias and potentially serve as models to test new treatments for these common disorders." (PMID 39278969, 2024). "Abnormal expressions of RyR2 often lead to an abnormal opening frequency of its channel and ultimately calcium leakage in the diastolic phase, causing ectopic discharge, which leads to the occurrence and maintenance of arrhythmia." (PMID 37598173, 2023). "Therefore, this study primarily investigated a direct role of O-GlcNAcylation of RyR2, a Ca2+ release channel frequently linked to arrhythmias is other settings." (PMID 37833717, 2023). "Importantly, similarities in cluster remodelling are observed in models of failure and arrhythmia, as detailed above, both of which are associated with increased Ca2+ leak via RyR2." (PMID 37890552, 2023). "A disruption of RyR2-FKBP interaction caused by oxidative stress may also contribute to RyR2 leak and cardiac arrhythmia caused by palmitoyl-carnitine." (PMID 37891912, 2023). "Thus, ROS can increase the open probability of RyR2 which results in an increase in intracellular Ca2+ and, consequently, leads to a higher Ca2+ binding to myofilament TnC, improving the risk of arrhythmias." (PMID 35047109, 2022). "In addition, other authors identified S-nitrosylation and calstabin 2 as a cause of RyR2 Ca2+ leakage leading to sudden cardiac arrhythmias in mdx mice." (PMID 36419836, 2022). "To unravel the molecular mechanisms underlying the selective perturbation of the recognition between CaM and RyR1 or RyR2 in arrhythmia-associated conditions, we focused on a CaM binding target region comprising 31 amino acids with a very similar sequence in the two RyRs (known as CaMBD2)." (PMID 36685279, 2022). "Furthermore, the inhibition of NOS1 in the SR decreased RYR2 activity because of reducing Ca2+ sparks and shortened action potential causing arrhythmia susceptibility." (PMID 35924220, 2022). "Whether the modulation of RyR2 by these agents increases the risk of arrhythmias and SCD remains to be explored." (PMID 36613717, 2022). "Therefore, the CPVT-associated CaM variants N53I and A102V not only increase the RyR2 Po but also cause changes in Ca2+ release dynamics at a global cellular level, which will contribute to the arrhythmia phenotype." (PMID 34888671, 2022). "Determining the mechanisms by which RYR2 variants can lead to arrhythmias is important as treatment efficacy may be dependent on the underlying mechanism which leads to arrhythmias." (PMID 35439358, 2022). "The remainder of this mini-review focuses on how changes in RyR2 behavior, associated with specific mutations, RyR2 modulators, and beta-adrenergic signaling, produce diverse phenotypes and potentially fatal cardiac arrhythmias with involvement from Ca2+ sparks and Ca2+ waves." (PMID 35892340, 2022). "Mutations in RyR2 are associated with both cardiac arrhythmias and intellectual disability." (PMID 35233070, 2022). "Three individuals with RYR2 mutations in the present study showed arrhythmia." (PMID 33897349, 2021). "This is in agreement with recent experimental data from a novel murine model with cardiac‐specific, tamoxifen‐triggered PKP2 deficiency: PKP2 deficiency increased RyR2‐mediated Ca2+ release from the sarcoplasmic reticulum, leading to catecholamine‐induced arrhythmias." (PMID 33784018, 2021). "On the other hand, RyR2-R2474S+/– knockin mice exhibiting catecholamine-induced intracellular Ca2+ leak subsequently revealed mitochondrial dysfunction, increased ROS production, increased atrial RyR2 channel oxidation, and arrhythmia susceptibility." (PMID 34955889, 2021). "The extent of RyR2 variants responsible for cardiac arrhythmias and cardiomyopathies as well as the various underlying pathogenic mechanisms remains unknown." (PMID 34202968, 2021).
Arrhythmia (continued). "In addition, loss of function (LOF) RyR2 mutations have also been identified and recently linked to a distinct entity of cardiac arrhythmia termed ‘RyR2 Ca2+ release deficiency syndrome’ (CRDS))." (PMID 34202968, 2021). "We tested the hypothesis that ET could stabilize RyR2-dependent SR Ca2+ release associated with arrhythmias in post-MI HF rats." (PMID 33569394, 2020). "However, the RyR2 mutation not only caused life-threatening arrhythmia but also affected the structure of the myocardium." (PMID 31143551, 2019). "However, when the RyR2-mutated mice undergo exercise fatigue or epinephrine stimulation, spontaneous Ca2+ release disorders often cause arrhythmias." (PMID 31143551, 2019). "Our study suggested that an I/R-injured myocardium was more susceptible to VT with a higher expression of ox-CaMKII, p-CaMKII, and p-RyR2 (Ser2814) while upregulation of miR-145 dramatically decreased the activation of CaMKII and RyR2 (Ser2814) thus reducing the risk of arrhythmia." (PMID 31583047, 2019). "Genetic analysis and single-channel measurement of RYR2 activity revealed that the combination of these polymorphisms in a single individual led to a leaky SR channel under diastolic conditions, thereby triggering arrhythmia and sudden cardiac death." (PMID 31426283, 2019). "Since the changes in RyR2 channel regulation that occur during ischaemia may contribute to the changes in intracellular [Ca2+] that predispose towards arrhythmias, it is important to understand how ATP and its metabolites affect RyR2 gating." (PMID 30301919, 2018). "Ca2+ deregulation is a critical hallmark of cardiac arrhythmias and dysfunction of the regulatory proteins involved in Ca2+ homeostasis, including ryanodine receptor type 2 (RyR2), IP3R, and CAMKII, which may lead to the development of AF." (PMID 30572675, 2018). "However, it has been shown that even extremely small quantities of CaMKII can activate RyR2 by phosphorylation, which has been implicated in arterial fibrillation, cardiac arrhythmia, cardiac hypertrophy and heart failure." (PMID 25750702, 2015). "Compartmental reduction of SERCA2 and RyR2 expression may contribute to arrhythmia heterogeneity with the LV being at greater risk of arrhythmia initiation on the basis of spontaneous calcium leak compared to RV ectopy." (PMID 24427266, 2014). "Furthermore, low aerobic capacity in LCR rats led to an increased diastolic SR Ca2+ leak over the RyR2, which has been linked to cardiac arrhythmias in several studies on left ventricular myocytes." (PMID 24146891, 2013). "In the final analysis, the pathological changes in RyR2 which cause spontaneous diastolic leak and arrhythmia must be understood from a perspective which correlates the dynamics of RyR2 channel gating with intramolecular movement, and this presents an intriguing challenge." (PMID 19345240, 2009). "Several RYR2 variants also predispose to Ca++ leakage, particularly under conditions of elevated catecholaminergic activity—for example, exercise and emotional stress that, in turn, may result in fatal cardiac arrhythmias." (PMID 41561974, 2025). "Therefore, we tested whether an oxidation‐resistant form of CaMKII protects mice carrying the CPVT1‐causative mutation RyR2‐R2474S (RyR2‐RS) against arrhythmias." (PMID 34558218, 2021). "In conclusion, our clinical and laboratory study of a four‐generation family with a novel RYR2 (c.527G > T, p.R176L) variant provided a unique opportunity to explore the mechanisms of disease, penetrance, and variable presentation in this rare, but highly malignant inherited arrhythmia condition." (PMID 31994352, 2020). "Although the structural impact of the exon-3 deletion and its effect on spontaneous Ca2+ release in the heterologous HEK293 cells have been well characterized, the mechanisms by which the exon-3 deletion in RyR2 causes cardiac arrhythmias and cardiomyopathy are unknown." (PMID 24743769, 2014).
Arrhythmia (continued). "However, some RyR2 mutations have been linked to cardiomyopathies as well as cardiac arrhythmias." (PMID 24743769, 2014). "Several studies on ventricle cardiomyocytes and also from patients with atrial fibrillation have shown that increased RyR2 Ca2+ leak from the SR during diastole is a potent trigger for uncontrolled electrical activity that may cause spontaneous contractions and arrhythmias." (PMID 24146891, 2013). "The mutations that cause LOF of the RYR2 channel are linked to a separate form of cardiac arrhythmia called RyR2 Ca2+ release deficiency syndrome (CRDS), which differs from CPVT caused by GOF RYR2 mutations." (PMID 41510139, 2026). "These genetic alterations in RYR2 can result in a spectrum of arrhythmias which also follows an autosomal dominant (AD) inheritance pattern." (PMID 40910028, 2025). "Spontaneous Ca2+ release through the cardiac ryanodine receptor (RyR2), termed “storage overload-induced Ca2+ release”, is a common mechanism of arrhythmia." (PMID 39211774, 2024). "It is believed that an increased SR Ca2+ load during rapid pacing combined with the increased RyR2 open probability leads to arrhythmia." (PMID 39590361, 2024). "The gain-of-function mutation in the RyR2 proteins that increases the opening probability of RyR2 channels and increase propensity towards the cytosolic Ca2+ ends up developing an arrhythmia during rapid pacing with β-AR stimulation." (PMID 39590361, 2024). "Arrhythmias induced by silmitasertib (a casein kinase 2 inhibitor) and sunitinib have been reported to result from their effects on RyR2 and increased storage overload-induced Ca2+ release." (PMID 39211774, 2024). "ISO-challenged RyR2-R2474S/+ showed increased incidence of arrhythmia accompanied by abnormal Ca2+ transients compared to WT." (PMID 39697246, 2024). "In the heart, genetic or acquired mishandling of diastolic [Ca2+] by ryanodine receptor type 2 (RyR2) overactivity correlates with risks of arrhythmia and sudden cardiac death." (PMID 38012000, 2024). "Although not currently clinically approved for HF treatment, selective RyR2-targeting drugs provide an interesting prospect for preventing Ca2+ leak in failing hearts and other ryanopathies, including arrhythmia." (PMID 37890552, 2023). "In the process of detecting the RyR2 mRNA levels, cAMP and adrenaline closely related to arrhythmia in this pathway were quantitatively determined." (PMID 37598173, 2023). "In contrast, studies from different labs have provided evidence that CaMKII phosphorylation of RyR2 at Ser-2814 exacerbates RyR2 leak and contributes to multiple cardiac dysfunctions including heart failure and arrhythmias." (PMID 36672139, 2023). "Therefore, it was assumed that abnormal opening of RyR2 channels was one of the pathogenic mechanisms of arrhythmia caused by BaCl2, and that the improvement of RyR2 channel function by inhibiting the overexpression of RyR2 mRNA might be a potential mechanism of the antiarrhythmic action of FSM." (PMID 37598173, 2023). "Phosphorylation of RyR2 at Ser2814 [site for calcium/calmodulin-dependent protein kinase II (CaMKII) activation] triggers the increased diastolic SR Ca2+ leak and provokes cardiac arrhythmias." (PMID 37303604, 2023). "We selected propranolol, verapamil, flecainide for their potency to prevent cardiac arrhythmias in patients and S107 for its efficacy in preventing RyR2 Ca2+ leak experimentally." (PMID 37740238, 2023). "This inappropriate RyR2 activation results in diastolic SR Ca2+ leak, which has been suggested to trigger fatal cardiac arrhythmias." (PMID 36982484, 2023). "It is likely CaMKII phosphorylation of RyR2 further aggravates the defects of the channel complex caused by CPVT mutations, thus, contributing to cardiac arrhythmias." (PMID 36672139, 2023).
Arrhythmia (continued). "Although these data indicate that HIV-Tat, ATV, EFV, and RTV can modulate RyR2 in cardiac myocytes, additional studies in clinically relevant models must be conducted to determine if these drugs are capable of triggering arrhythmias and even SCD." (PMID 36613717, 2022). "Increased Ca2+ leakage from the SR through the RyR2 channel is considered an important mechanism of arrhythmia, and RyR2 phosphorylation plays a key role in regulation of SR Ca2+ release." (PMID 36225189, 2022). "This study showed that the occurrence of arrhythmia after ischemia was closely related to phosphorylation of RyR2 (Ser2808) and RyR2 (Ser2814) by CaMKII, which promoted dissociation of the FKBP12.6-RyR2 complex, and increased intracellular Ca2+ content." (PMID 36225189, 2022). "Hyperphosphorylation of p-RyR2 (Ser2808) and p-RyR2 (Ser2814) is an important contributor to arrhythmia induced by abnormal RyR2 function." (PMID 36225189, 2022). "Disturbances in finely-tuned SR Ca2+ release by SR Ca2+ channel ryanodine receptor (RyR2) and SR Ca2+ reuptake by SR Ca2+-ATPase (SERCa2a) not only impair contraction, but also contribute to cardiac arrhythmia trigger and reentry." (PMID 36425292, 2022). "Statins also reduced the ryanodine receptor-2 (RyR2) cardiac activity, and this suppressed cardiac arrhythmias." (PMID 35163340, 2022). "Abnormal functioning of RYR-2 will result in imbalance of intracellular calcium ion homeostasis, leading to arrhythmia, cardiac hypertrophy, heart failure, and other heart abnormalities." (PMID 33897349, 2021). "The RYR2 mutations have been established in the etiology of ARVD2 and CPVT, in which arrhythmia was common." (PMID 33897349, 2021). "Here, we propose a role for RyR2 dysfunction and NCX modulation as potential targets for the prevention/treatment of arrhythmias resulting from loss of PKP2 function." (PMID 34630150, 2021). "A previous study, however, found that PDE4D3 is part of macromolecular cardiac RyR2 signaling complex, and PDE4D-KO mice develop heart dysfunction and arrhythmias, resulting from RyR2 hyperphosphorylation at Ser2808." (PMID 34445119, 2021). "Several preclinical studies have utilized these RyR2-binding proteins to stabilize RyR2 in treating arrhythmia and heart failure." (PMID 34200203, 2021). "Surprisingly, RyR2‐RS/MMVV mice showed a similar increase in arrhythmia score and incidence of VT compared to WT (9/12)." (PMID 34558218, 2021). "Especially, CaMKII facilitates INaL, as well as SR Ca2+ leak from RyR2 via phosphorylation in HF, thereby provoking arrhythmia." (PMID 34062838, 2021). "Similar to the previous test, both RyR2‐RS and RyR2‐RS/MMVV showed increased arrhythmia score and increased incidence of VT compared to WT." (PMID 34558218, 2021). "As expected, RyR2‐RS mice exhibited an increased incidence of ventricular arrhythmias indicated by increased arrhythmia score compared to WT." (PMID 34558218, 2021). "It was reported that mutant leaky RyR2 channels were found in HF patients, and leaky RyR2 played a critical role in the pathogenesis of cardiac arrhythmias and impaired glucose metabolism." (PMID 33860059, 2021). "RyR2 is also a critical player in the pathogenesis of various cardiac arrhythmias and cardiomyopathies." (PMID 33825858, 2021). "Other studies have also reported that in vitro oxidation of RyR2 increases the channel response to cytoplasmic Ca2+ concentration and favors Ca2+ release in isolated cardiomyocytes, generating Ca2+ waves and arrhythmias." (PMID 33274235, 2020). "This diastolic Ca2+ leak from the SR through dysfunction of RyR2 is important in the pathogenesis of arrhythmia and heart failure." (PMID 32885578, 2020). "While no results have yet been posted, the study highlights the potential of RyR2 inhibition for the treatment of arrhythmias." (PMID 33013458, 2020).